ATG5 (autophagy related 5)
Diseases named in the same sentence as ATG5 in open-access papers (continued):
Sharing a sentence is not in itself a finding about the gene and the disease.
colorectal cancer (26 papers, 2012 to 2024). A primary or metastatic malignant neoplasm that affects the colon or rectum. "For example, ATG5 gene deletions or mutations of autophagy‐related tumor suppressor gene URAG have been frequently observed in colorectal cancer." (PMID 36760166, 2023). "ATG5 point mutations were detected in biopsies of patients with hepatocellular carcinoma, gastric and colorectal cancers, suggesting the potential involvement of ATG dysregulations in abnormal autophagy and tumor development." (PMID 34685652, 2021). "Herein, we investigated the association of the ATG5 protein level with the overall survival and disease-free survival in patients with colorectal cancer." (PMID 33926066, 2021). "Our present results suggest that a high ATG5 was associated with poor survival in colorectal cancer patients with early stages." (PMID 33926066, 2021). "In addition, downregulation of ATG5 protein and mutations in the ATG5 gene have also been linked with prostate and colorectal cancers." (PMID 35632737, 2022). "Two SNPs in ATG5 (rs2241880 and rs2245214) have been associated with a nearly twofold susceptibility to nonmedullary thyroid cancers 19 and rs2241880 is associated with disease severity 18 as well as two‐fold risk of developing colorectal cancer." (PMID 27748080, 2016). "Thus, further study may be required for the mutation and function of ATG5 in tumor tissues of colorectal cancer." (PMID 33926066, 2021). "Thus, the association of ATG5 protein in prognosis and the function in colorectal cancer remains unclear." (PMID 33926066, 2021). "Atg5 has been shown to be a tumor suppressor including down‐regulation of Atg5 in colorectal cancer patients and early‐stage cutaneous melanoma." (PMID 38826147, 2024). "A similar result was reported in patients with sporadic colorectal cancer, i.e., Atg5 was markedly downregulated." (PMID 38826147, 2024). "A comparison between colorectal cancer mice models ApcMin with mice models with heterozygous deletions of Atg5 (Atg5+/−) and also ApcMin mice with Atg5+/+ showed an increase in the number and size of adenomas in Atg5+/− mice." (PMID 36760166, 2023). "Another previous study showed that stable knockdown of ATG5 can significantly inhibit the occurrence and progression of colorectal cancer tumours in vivo." (PMID 35592424, 2022). "Nevertheless, the full length ATG5 mRNA and protein levels are decreased in tumor tissues compared to normal tissues in patients with colorectal cancer." (PMID 33926066, 2021). "Fourth, silencing the ATG5 diminished the tumorsphere formation and sensitized colorectal cancer cells to chemotherapeutic agents." (PMID 33926066, 2021). "Confirming the results with the autophagy inhibitors spautin and 3‐MA, ATG5‐depleted colorectal carcinoma cells had a reduced content of LC3B after exposure to NVP or NVP‐iso compared to control nonsilenced cells." (PMID 31545551, 2019). "Down-regulation of ATG5 has been found in colorectal cancer and early-stage cutaneous melanoma tissue compared to their normal counter parts." (PMID 29207660, 2017). "Third, a very recent paper has shown that overexpression of the colorectal-cancer-associated truncated form of UVRAG promotes tumorigenesis independently of autophagy status, that is, both in control and Atg5-knockout cells." (PMID 26921396, 2016). "ATG5 is a prognostic indicator of squamous cell carcinoma, prostate, and colorectal cancers relapse." (PMID 27120789, 2016). "Blocking autophagy with 3-MA in combination with anti-cancer drugs has been used against several types of cancer, e.g. breast and colorectal cancer, and siRNAs to silence the ATGs Beclin1 and Atg5 have been tested against cervical cancer." (PMID 22424437, 2012). "Interestingly, the negative regulation of the JNK signaling pathway suppresses the ATG5 and ATG12 expression in hippocampus of epileptic rats, and the ERK promotes the expression of ATG5 in the human colorectal cancer cell lines." (PMID 35762728, 2022).
colorectal cancer (continued). "Finally, we assessed the clinical relevance of ATG5 protein levels on the pathological stages and therapy with overall survival in colorectal cancer patients." (PMID 33926066, 2021). "In addition, colorectal cancer cells stably harboring small interfering RNA (siRNA) against ATG5 diminished the tumorsphere formation and sensitized cancer cells to chemotherapeutic agents." (PMID 33926066, 2021). "Our study suggested that the ATG5 protein might promote tumor progression and malignancy, which provide the ATG5 as a prognostic marker for patients with colorectal cancer." (PMID 33926066, 2021). "Taken together, these results suggest that the ATG5 may serve as a tumor suppressor in tumor imitation, whereas it serves as a tumor promoter in cancer metastasis and drug resistance of colorectal cancer." (PMID 33926066, 2021). "In colorectal cancer tissues, ATG5 expression was also downregulated, which led to the assumption that ATG5 may function as a tumor suppressor." (PMID 31137558, 2019). "Notably, elevated ATG5 was correlated with lympho vascular invasion even though ATG5 was decreased in colorectal cancer." (PMID 29207660, 2017). "Furthermore, the down-regulation of Atg5 expression has been shown in colorectal cancer and early cutaneous melanoma patients with prognostic and diagnostic implications." (PMID 26416459, 2015). "In addition, silencing the ATG5 diminished tumor sphere formation and sensitized colorectal cancer cells to chemotherapeutic agents, suggesting that ATG5 could be a therapeutic target for colorectal cancer." (PMID 33926066, 2021). "Specific inhibition of autophagy by 3-MA or shRNA targeting Atg5 rescued Sal B-induced cell death in vitro and in vivo, suggesting that Sal B-induced autophagy may play a pro-death role and contribute to the cell death of colorectal cancer cell lines." (PMID 27557491, 2016). "Separate evidence shows that the expression of ATG5 and ATG7, autophagy-related proteins, influences the prognosis of colorectal cancer." (PMID 34484469, 2021). "Pelareorep is one example that was recently demonstrated to increase the expression of autophagy-related proteins, such as LC3 and ATG5, in colorectal cancer cells, a phenomenon that boosts not only the propagation of reovirus but also cell death." (PMID 34685652, 2021). "A study of colorectal cancer, using an Abcam LC3B polyclonal antibody, found negative LC3B expression and absence of autophagy related proteins (Beclin 1 ATG5 LC3B) are associated with poor survival." (PMID 26265176, 2015).
glioblastoma (25 papers, 2013 to 2025). The most malignant astrocytic tumor (WHO grade IV). "By contrast, knockdown of ATG5 increased migration and invasion in glioblastoma cells and RAS-mutated cancer cells by promoting EMT." (PMID 34901004, 2021). "SF-295 glioblastoma cells showed caspase-3 activation and evidence of apoptotic cell death in a pattern that was also seen in wild-type and autophagy-deficient (ATG5-null) MEFs." (PMID 23762328, 2013). "Contrary to this, other studies showed that dual inhibitor (NVP-BEZ23) of the P13K/mTOR signaling pathway can enhance autophagy through affecting the ATG5 and Beclin1 autophagy-linked proteins and DNA damage repair proteins functions, and can stimulate the radiation sensitive glioblastoma cells." (PMID 33525678, 2021). "STAT3 is involved in the expression of the autophagy-related gene ATG5 in Glioblastoma multiforme stem cells." (PMID 40727105, 2025). "Immunohistochemical staining revealed that LC3B and ATG5 expression levels increased with glioblastoma grade, whereas cleaved caspase‐3 (C‐Caspase3) expression decreased." (PMID 40990506, 2025). "Abolishing autophagy in ATG5 KOs reversed the bortezomib-induced toxicity, rescued glioblastoma cell death and reduced animal survival." (PMID 36619857, 2022). "Here, we aimed to assess the potential association between several candidate polymorphisms in autophagy genes (ATG2B rs3759601, ATG16L1 rs2241880, ATG10 rs1864183, ATG5 rs2245214, NOD2 rs2066844 and rs2066845) and glioblastoma susceptibility." (PMID 35123435, 2022). "It has been found that the HIF-1α/miR-224-3p/ATG5 pathway impacts the mobility of cells by regulating hypoxia-induced autophagy in glioblastomas and astrocytomas." (PMID 34949203, 2021). "Knockdown of ULK1, ATG5, or Ambra-1 conferred protection of glioblastoma cells from THC-induced cell death." (PMID 28674677, 2017). "In this study, we have analyzed common polymorphisms in genes involved in autophagy (ATG2B rs3759601, ATG16L1 rs2241880, ATG10 rs1864183, ATG5 rs2245214, NOD2 rs2066844 and rs2066845) in order to evaluate their role in the susceptibility to suffer glioblastoma." (PMID 35123435, 2022). "CREBRF acts as a tumor suppressor of glioblastoma through the suppression of ATG5 and CREB3." (PMID 36358691, 2022). "MiR‐224‐3p inhibits hypoxia-induced autophagy by directly targeting a key regulator of autophagy, an autophagy-related 5 (ATG5) gene that may be a novel target against hypoxia-induced autophagy in glioblastoma and astrocytoma." (PMID 34949203, 2021). "When these VZV data about IL-6/STAT3/ATG5 are considered together with the results from the glioblastoma/autophagy study, we conclude that the elevated levels of IL-6 may also facilitate elevated levels of autophagy in VZV-infected skin explants." (PMID 30568636, 2018). "Autophagic genes, including Atg5, Atg7, and ULK, are overexpressed in detached cells from glioblastoma, thus preventing anoikis and promoting tumour growth." (PMID 37174088, 2023). "miR-33a and miR-224-3p overexpression inhibits the tumour suppressor UVRAG and the ATG proteins Atg5 and FIP200, respectively, and correlates with poor prognosis in glioblastomas." (PMID 37174088, 2023). "MiR-224-3p suppresses ATG5 and FIP200, thereby inhibiting autophagy, and its overexpression restrained the tumorigenesis in glioblastoma cells." (PMID 33525678, 2021). "miR-224-3p inhibited autophagy by suppressing ATG5 and FIP200, and its overexpression inhibited tumorigenesis in glioblastoma cells." (PMID 32707662, 2020). "Conditioned media from TMZ-treated shNC cells significantly enhanced glioblastoma cell proliferation and migration compared to media derived from TMZ-treated shATG5 cells, suggesting that TMZ induces ATG5-dependent secretion of specific factors that remodel tumor behavior." (PMID 41353343, 2025). "Silencing autophagy-related genes Atg5 and Atg7 enhances apoptosis, suggesting that autophagy may act as a protective mechanism in CB2R-expressing glioblastoma cells." (PMID 40483537, 2025).
glioblastoma (continued). "As expected, we found that ATG5 overexpression or knockdown did not affect UTMD-induced cell death or reduction of colony formation in IR-treated glioblastoma cells (P > 0.05)." (PMID 35152910, 2022). "We investigated the requirement of functional autophagy machinery by utilizing pharmacological inhibitors or CRISPR-Cas9 knockout (KO) of autophagy-related genes -5 and -7 (ATG5 and ATG7) in glioblastoma cells and monitored changes in autophagic flux after temozolomide and/or bortezomib treatments." (PMID 36619857, 2022). "Besides glioblastoma, (−)-gossypol was shown to trigger ACD in apoptosis-resistant prostate cancer and breast carcinoma cells, as silencing of ATG5 and BECN1 significantly rescued (−)-gossypol-mediated cell death." (PMID 28674677, 2017). "To verify the precise effect of altered autophagy in SH-mediated cell death, we investigated the role of RNA interference against Beclin-1 and ATG5 or an autophagy activator (Rapa) and autophagy inhibitors (3-MA, WORT and CQ) in SH-induced glioblastoma cell death." (PMID 28891980, 2017). "A study comparing the effects of curcumin and solid lipid curcumin particles on autophagy and mitophagy in glioblastoma multiforme cells showed that SLCPs demonstrated superior induction of autophagy markers (Atg5, Atg7, Beclin-1, and LC3A/B) compared to Cur in U-87MG, GL261, and F98 GBM cell lines." (PMID 40227413, 2025).
Obesity (25 papers, 2013 to 2026). Accumulation of substantial excess body fat. "In line with the phenotypes observed in TFEB-Tg mice and in Atg5-Tg mice, liver-specific Raptor KO mice are resistant to diet-induced obesity and to hepatic steatosis, and these effects are, at least in part, mediated by the mTORC1 target Lipin1." (PMID 34277603, 2021). "On the other hand, we observed a null response in atg5 and lc3b mRNA expression, which was unexpected given their well-reported role as markers of induced autophagy in AT in obesity condition." (PMID 33076271, 2020). "A study in AT from patients with obesity showed greater mRNA expression of the autophagy-related genes Atg5, lc3a and lc3b than their lean counterparts, as well as in visceral versus subcutaneous depot." (PMID 33076271, 2020). "A previous study on mice with adipose-specific knockout of autophagy-related 5 (Atg5) and Atg7 showed that the effect of anti-IR and anti-obesity could effectively regulate fat mass via autophagy." (PMID 37484964, 2023). "Hypothalamic pro-opiomelanocortin neuron (POMC)–specific Atf4-KO mice are resistant to high-fat diet–induced obesity via enhanced autophagy-related 5-dependent autophagy and α-melanocyte–stimulating hormone production, suggesting that ATF4 in POMC neurons negatively regulates energy expenditure." (PMID 34547510, 2021). "Consistently, ubiquitous and moderate overexpression of Atg5 in mice, resulting in increased autophagy, leads to a leaner phenotype, an increased glucose tolerance and insulin sensitivity, and resistance to age-induced obesity." (PMID 34277603, 2021). "Previous studies showed that diabetes impaired hepatic autophagy and that obesity caused markedly decreased autophagy in livers of both genetic and dietary mice models; this effect was demonstrated by decreased expression levels of LC3 and Atg5." (PMID 32194395, 2020). "It has been reported that atg5 mRNA may be clinically relevant in obesity, since it explains about 50% of visceral adiposity and adipocyte hypertrophy." (PMID 33076271, 2020). "In addition, knockdown of autophagy genes Atg5 and Atg7 in adipocytes can improve insulin sensitivity and relieve obesity." (PMID 27843198, 2016). "Posttranslational events could be involved in regulating autophagy in obesity or autophagy could be disrupted at a later point such as ATG5–12 conjugation, LC3 processing or autophagosome/lysosome fusion." (PMID 25786112, 2015). "In accordance with results from studies in human obesity, we found an increase of Atg5 and Atg7 expression in visceral adipose tissue of WOKW rats, suggesting parallel alterations in the endocrine function of adipose tissue both in human and in WOKW metabolic syndrome." (PMID 23668414, 2013). "Likewise, the deletion of autophagy-related ATG5 or ATG7 in hypothalamic POMC neurons is found to trigger abnormal glycolipid metabolism and severe obesity in the ATG5-or ATG7-deficient mice, suggesting the involvement of ER-phagy in the degradation of misfolded POMC." (PMID 37152279, 2023). "To investigate the effects of obesity and THC on autophagy, we measured the expression of the autophagy-related factors LC3, Beclin 1, and Atg5." (PMID 34222477, 2021). "Significant evidences links obesity and T2DM with autophagy, where ATG5 plays a certain role disease development." (PMID 30386331, 2018). "While pharmacological inhibition, silencing or knockdown of ATG5 in hepatocytes results in increased triglyceride levels and lipid droplet accumulation, WAT expression of ATG5 is increased in obesity, especially in the VAT depot, and is a key regulator of adipogenesis." (PMID 34638880, 2021). "As shown in our data, the mRNA levels of autophagic genes (Atg5, Atg7, Beclin1, and Tfeb) were found to be remarkably increased in the HFD + DSS group compared with the HFD group, suggesting that uptake of fatty acids triggers autophagy in obesity-related colitis." (PMID 34451919, 2021).
Obesity (continued). "Furthermore, several autophagy markers, including ATG5, are increased in visceral AT as well as subcutaneous AT of obese and T2DM patients, suggesting ATG5-dependent autophagy might be involved in the development of obesity-induced T2DM." (PMID 30386331, 2018).